TLR4 (toll like receptor 4)
Diseases named in the same sentence as TLR4 in open-access papers (continued):
Sharing a sentence is not in itself a finding about the gene and the disease.
diabetes (continued). "TLR4, a pattern recognition receptor known for its role in innate immunity, is activated under metabolic stress conditions such as diabetes." (PMID 40855901, 2025). "In summary, targeting the gut microbiota-TLR4 axis is a fascinating potential complementary strategy for diabetes." (PMID 41459531, 2025). "First, we induced diabetes in C3H.HeJ mice, which are mutants of the Lps locus in TLR4, making them hyporesponsive to stimulation with LPS, and in C3H.He mice that is the genetic background of C3H.HeJ mice." (PMID 40496562, 2025). "Diabetes induction was achieved through the intravenous injection of alloxan, followed by treatments with antibiotic therapy or TLR4 antagonist (TAK-242) for 14 consecutive days." (PMID 40496562, 2025). "The chronic inflammatory response triggered by TLR4 contributes to the onset of age-related disorders, like Alzheimer’s disease, cancer, osteoarthritis, myocardial disorders and diabetes." (PMID 40149697, 2025). "To investigate the impact of TLR4 on DPN, we induced diabetes in wild-type and TLR4 knockout (TLR4-/-) mice using streptozotocin." (PMID 41167527, 2025). "Overview of selected pharmacological interventions targeting the gut microbiota and TLR4/NF-κB signaling pathway in diabetes, highlighting their sources, mechanisms of action, therapeutic effects." (PMID 41459531, 2025). "This pattern aligns with TLR4′s known role in innate immunity-driven systemic diseases like diabetes mellitus and psoriasis." (PMID 41002387, 2025). "Treatment with CCP by and large reversed these diabetes-induced changes, presumably by inhibiting the TLR4/NF-κB signaling pathway." (PMID 39852351, 2025). "This review highlights how the gut microbiota–TLR4 axis is a multifaceted therapeutic target for diabetes." (PMID 41459531, 2025). "This review aims to synthesize current understanding of targeting the gut microbiota– Toll-like receptor 4 (TLR4) axis in diabetes." (PMID 41459531, 2025). "In the existing literature, several researchers elaborate extensively on the significance of the gut microbiota–TLR4 axis in the onset and progression of diabetes mellitus and especially type 2 diabetes (T2DM)." (PMID 41459531, 2025). "Other studies show that macrophages are a dominant source of TLR4 expression in islets from healthy mice and humans, as well as in islets from individuals with diabetes." (PMID 40387904, 2025). "Both TLR4 and oxLDL levels are elevated in diabetes, and an increase in circulating LDL, which is a precursor of oxLDL, is a risk factor for diabetic neuropathy." (PMID 38525707, 2024). "Research has found that NAD(P)H quinone oxidoreductase 1 mitigates diabetes-induced renal inflammation and fibrosis by modulating the Toll-like receptor 4 (TLR4)/NF-κB and TGF-ß/Smads signaling pathways." (PMID 39712489, 2024). "Further evidence links HSP70 to the development of diabetes and vascular diabetic complications through the Toll-like receptor 4 (TLR4) pathway." (PMID 39765892, 2024). "The activation of diabetes-related mediators, including toll-like receptor 4 (TLR4), NLRP3, caspase-1, IL-1β, IL-18, and GSDMD-NT, plays a pivotal role in the pathophysiology of DKD." (PMID 39201721, 2024). "Blocking TLR4 alleviated the changes in body weight and blood glucose, consequently reducing the efficiency of diabetes modeling, especially for male mice." (PMID 38275739, 2024). "Previous studies have shown that activation of the TLR4/NF-κB signaling pathway is related to the pathogenesis of IR and diabetes." (PMID 39429784, 2024). "This study confirmed that the knockout of the TLR4 gene significantly alleviated the overweight and hyperlipidemia/hypoglycemic syndromes in mice during the process of constructing obese/diabetes models." (PMID 38275739, 2024). "There is compelling evidence that activation of the TLR4/NF-κB signaling pathway is related to the pathogenesis of IR and diabetes." (PMID 39429784, 2024).
diabetes (continued). "Both chronic and acute administration of LPS in animal models mimics the pathological hallmarks of diabetic retinopathy (DR) or exacerbates existing retinopathy in diabetes by targeting Toll-like receptor 4 (TLR4)." (PMID 38336763, 2024). "Renal inflammation in diabetes has been linked to NOX5, particularly via activation of the TLR-4-dependent pathway." (PMID 38671844, 2024). "In the TLR4 knockout diabetes mice, the infiltration of interstitial macrophages, proteinuria, and progress of renal function was significantly improved." (PMID 37538798, 2023). "Multiple molecular studies have been performed on SNPs present in the TLR4 gene, and limited studies have documented different forms of diabetes." (PMID 37830554, 2023). "Possibly, the activation of TLR4 in the Schwann cells and spinal cord of diabetics induces an overproduction of TNF-α, resulting in the increase of pain." (PMID 36946851, 2023). "In contrast to what was observed in the hippocampus, the relative mRNA expression of TLR4 and TNFα in the cerebral cortex was significantly increased by short-term diabetes." (PMID 36674713, 2023). "Possibly, the activation of TLR4 in the hippocampus of diabetics induces an exacerbation in the neuroinflammation and glutamatergic transmission, resulting in the aggravation of depressive symptoms and in the development of the treatment-resistant depression." (PMID 37892186, 2023). "In diabetes, the proportion of TLR4-positive myenteric neurons changed significantly in all observed gut regions." (PMID 36672637, 2023). "High mobility group box 1 (HMGB1), a DAMP known to be elevated in diabetes, is released upon corneal injury and also acts via TLR4 to initiate inflammation." (PMID 36982926, 2023). "In diabetics, the distribution of TLR4-labelling gold particles between the perikaryon and neuropil of myenteric neurons varied in a different way by intestinal segment." (PMID 36672637, 2023). "TNFα levels were increased in the small intestine and decreased in colonic ganglia in response to diabetes similarly to TLR4 expression." (PMID 36672637, 2023). "The goal of the study was an analysis of the expression and functional activity of TLR2 and TLR4 on the cells of peripheral blood of patients with bronchial asthma (BA), type 2 diabetes mellitus (T2DM), and a combination of both diseases (BA + T2DM)." (PMID 36836906, 2023). "To examine the effect of the hyperglycemia accompanying diabetes on the activation of TLR4 by HMGB1, we performed similar experiments in medium with high (4.5 g/L)—or normal (1 g/L)-glucose concentration." (PMID 36982926, 2023). "In the diabetes cognitive impairment model, the level of TLR4 expression in microglia is increased under a high glucose environment, and the inflammatory response is activated by associated inflammatory factors such as NF-kB and MCP-1." (PMID 37576498, 2023). "Toll-like receptor 4 (TLR4) signaling plays a crucial role in pro-inflammatory signaling and the development of hypertension and diabetes, both contributing to CMDs." (PMID 37892006, 2023). "This study established diabetes models using rats and H9c2 cells in which the function of adiponectin/miR-711/TLR4 axis was analyzed." (PMID 36114541, 2022). "Activation of β-adrenergic receptor (β-AR) by administering an agonist compound-49b inhibits diabetes-activated TLR4 signalling in mice retina." (PMID 38983565, 2022). "There is a substantial amount of evidence showing increased expression of TLRs, in particular TLR4, in models of diabetes in both human and mouse retinal cells, along with increased expression of molecules downstream to TLR." (PMID 38983565, 2022). "In summary, we have shown that diabetes increases the interaction between MyD88 and TLR4 to initiate inflammatory injury in cardiomyocytes." (PMID 36180407, 2022).
diabetes (continued). "Visfatin, a multifunctional adipokine, causes in vitro endothelial dysfunction and vascular inflammation in obese and type 2 diabetes mellitus animal models through TLR4 activation." (PMID 35528818, 2022). "For instance, in research relating to diabetes, KLF7 can directly bind to the promoter region in IL-6 and accelerate the overexpression of IL-6 in inflammatory signaling TLR4/NF-kB/IL-6, thereby causing inflammation." (PMID 35419025, 2022). "LPS as a typical PAMP mainly from the cell wall of Gram-negative bacteria is found to be elevated in the circulation of people with diabetes and increases increased intestinal permeability through the activation of TLRs, mainly TLR4." (PMID 36406423, 2022). "For instance, vitD decreased expression of TLR2 and TLR4 on the monocytes of the patients suffering from type 2 diabetes mellitus and latent autoimmune diabetes." (PMID 35126351, 2021). "The activation of diabetes-mediated related factors such as TLR4, NLRP3, caspase-1, IL-1β, IL-18, and GSDMD-NT plays a vital role in the pathophysiology of DKD." (PMID 33692782, 2021). "Dan improved diabetes mellitus–induced renal injury via regulation of miR‐140‐5p/TLR4 axis in in vitro and in vivo study." (PMID 34532027, 2021). "Others examined fluctuations in glucose concentration on the activation of TLR4-JNK pathway in mediating diabetes-related inflammation in macrophages using THP-1 cells (human monocytes)." (PMID 34557866, 2021). "Studies have shown that resveratrol can protect the cardiovascular tissues of rats with CHD and diabetes by downregulating the TLR4/MyD88/NF-κB signalling pathway." (PMID 34887932, 2021). "Toll-like receptor-4 (TLR4) (the most important type of TLRs in diabetes) induces the activation of meta-inflammation mediators, referred to the nuclear factor kappa B (NF-ҠB) signaling pathway." (PMID 33952324, 2021). "A study in diabetes showed a role of TLR4 in promotion of lipid metabolism and lipid accumulation through LPL expression and diabetes in cardiomyocytes of mice." (PMID 33395447, 2021). "It has been demonstrated in many studies that the TLR4/NF-κB axis inhibition alleviated the onset and progression of several diabetes concomitant diseases." (PMID 34692851, 2021). "In mice, FasL can be induced by TLR4 activation in CD5+CD1d+ Bregs and in the NOD mouse model can be activated with LPS (TLR4), resulting in TGFβ production, which inhibits Th1 responses and diabetes progression." (PMID 34616408, 2021). "In general, inflammatory pathways are attenuated in the TLR-KO genotype, such as cytokine and interleukin signaling and inflammatory processes, as demonstrated after brain injury or diabetes in TLR4-KO." (PMID 32780740, 2020). "Recent studies show that FoxO1 promotes inflammation during diabetes by enhancing TLR4‐mediated signalling." (PMID 33108705, 2020). "LPS derived from pathogenic bacteria, a causal link between gut microbiota and systemic low-grade inflammation, translocates to liver and binds to TLR-4 to induce inflammatory cascade reaction to ultimately lead to diabetes mellitus." (PMID 32028957, 2020). "Other research studies suggested that TLR4 is involved in many inflammatory diseases such as influenza, cancer, diabetes, and neurodegenerative diseases, thereby suggesting that its regulation (antagonism/inhibition) would have an impressive clinical impact." (PMID 32182943, 2020). "Increased levels of TLR4 and downstream accessory proteins have been reported to be increased in human diabetes and in experimental models." (PMID 32358497, 2020). "Oridonin exerts protective effects against diabetes-induced renal injury via the Toll-like receptor 4 (TLR4)/p38-mitogen-activated protein kinase (MAPK) and NF-κB signaling pathways." (PMID 32184902, 2020). "Here we examine the role of myeloid differentiation 2 (MD2), a co-receptor of TLR4, in high glucose (HG)- and diabetes-induced inflammatory cardiomyopathy." (PMID 32358497, 2020).
diabetes (continued). "What has remained elusive, however, is how TLR4 is activated by glucose or other factors in diabetes." (PMID 32358497, 2020). "Numerous studies have indicated increased levels of TLR4 pathway proteins in diabetes and cells exposed to HG11–15." (PMID 32358497, 2020). "The TLR4 signaling pathway can be stimulated by various factors, including activation during diabetes." (PMID 31973752, 2020). "In this work, we investigated the implication of the activation of TLR4 on diabetes onset by using CLI-095 in the NOD mouse model." (PMID 31852918, 2019). "More specifically, we assessed in vivo and in vitro, the impact of TLR4 blockade on the function of diabetogenic T lymphocytes, and evaluated its impact on insulitis and the development of diabetes." (PMID 31852918, 2019). "Pathogen-recognition receptors in diabetes have been widely studied, but little is known about the role of TLR4 in the pathogenesis of this disease." (PMID 31852918, 2019). "Treatment with TLR4 inhibitor not only prevents the infiltrative insulitis but also prevents the onset of diabetes." (PMID 31852918, 2019). "Diabetes exacerbated oxidative stress, the inflammatory response, and apoptosis after renal I/R by enhancing TLR4/NF-κB signaling and blocking the Nrf2/HO-1 pathway." (PMID 31441362, 2019). "We then assessed the impact of TLR4 inhibition on the islet inflammation prior to the onset of diabetes." (PMID 31852918, 2019). "The current study shows that Lf decreased diabetes-induced inflammation by inhibiting the TLR-4-NF-κB axis with subsequent reduction in serum proinflammatory cytokines; IL-1β, IL-6, and IL-18, in diabetic children." (PMID 30534206, 2018). "The proinflammatory role of TLR4/NF-κB pathway has been demonstrated to be involved in the progression of diabetes and diabetic complication." (PMID 29604956, 2018). "Macrophage activation mediated by TLR4-JNK signaling plays an important role during the progress of diabetes." (PMID 29850615, 2018). "More recently, it has been posited that palmitate can moderate tool-like receptor 4 (TLR4) signaling and can thus contribute to diabetes pathogenesis through regulation of the gluconeogenic genes." (PMID 28525987, 2017). "A recent experimental study in rats with diabetes and middle cerebral artery occlusion demonstrated that inhibition of the TLR4 signaling pathway significantly decreased neuronal cell apoptosis." (PMID 29113143, 2017). "In vivo inhibition of AGE generation with aminoguanidine, macrophage depletion with clodronate liposomes, and antibody-based blockade of Il-1β and Tlr4 attenuated diabetes-induced retinal Lgals1 expression in mice." (PMID 29170525, 2017). "Among these TLRs, TLR4 plays an important role in many inflammatory disorders, and system inflammation facilitated by TLR4 is involved in the pathophysiological process of diabetes." (PMID 28900628, 2017). "Several recent studies reported that TLR4 levels increased in patients with type 2 diabetes, suggesting that a high glucose concentration results in TLR4 activation in diabetes." (PMID 28785380, 2017). "In vivo inhibition of AGE generation with aminoguanidine, depletion of macrophages with clodronate liposomes, and antibody-based blockade of Il-1β and Tlr4 significantly attenuated diabetes-induced retinal Lgals1 expression in mice." (PMID 29170525, 2017). "Given the clinical availability of TAK-242, human trials are warranted to test the efficacy of TLR4 antagonists in functional gastrointestinal disorders and systemic diseases associated with a visceral hyperalgesic phenotype, such as IBS and diabetes." (PMID 27159520, 2016). "It is possible that these effects of diabetes are mediated by stimulation of TLR4 by endogenous ligands, and that there is cross-talk between TLR4 signaling and EP4 signaling in diabetes." (PMID 27351842, 2016). "1,25(OH)2D3 exhibited protective effects against diabetes-related liver injury, possibly through downregulation of components of the TLR4 signaling pathway." (PMID 25906757, 2015).
diabetes (continued). "Toll like receptor 4 (TLR4) has been shown to play an important role in diabetes and cardiovascular disease, and both fatty acids and LPS are ligands for TLR4 receptors." (PMID 26580567, 2015). "To further elucidate the function of TLR4 during DR, we performed bone marrow transplantation to create reciprocal chimeric TLR4 KO and TLR4 WT mice and then established the diabetic retina mouse model using STZ treatment." (PMID 25214718, 2014). "Understanding the regulation of cardiac TLR4 signaling during metabolic dysfunction will facilitate improved management of cardiac sequela to metabolic syndrome and diabetes." (PMID 25101057, 2014). "TLR2 and TLR4 play an important role in diabetic nephropathy, and especially in the high-fat diet-induced diabetes rat model, TLR4 and its downstream IKKβ/NF-κB pathway components are significantly activated." (PMID 24810370, 2014). "To determine the role of TLR2 and 4 in the pathogenesis of microangiopathy, we assessed for ICAM-1 expression in TLR2-/- and TLR4-/- murine models after the induction of diabetes." (PMID 25303153, 2014). "It has been shown that TLR4 and its signal pathway participated in the pathogenesis of diabetes and diabetic nephropathy." (PMID 24779014, 2014). "Further, diabetes appear to accelerate the capacity to produce cytokines in response to TLR4 as maximum levels are reached earlier in life in diabetic splenocytes compared to healthy." (PMID 24594974, 2014). "Sequences of oligonucleotides used for PCR analyses of TLR4 expression status and NOD-specific alleles of diabetes-associated loci." (PMID 24086519, 2013). "TLR4−/− mice showed a mean age of diabetes manifestation of only 118±21 d (p<0.01 compared to TLR4+/+ mice), representing an acceleration by 59 d." (PMID 24086519, 2013). "In the group of TLR4+/+ mice the first case of diabetes was observed at an age of 148 d, and until 210 d of age 71% of the animals had developed diabetes (mean age of diabetes manifestation 177±22 d)." (PMID 24086519, 2013). "In TLR4+/− mice the mean age of diabetes manifestation was 129±40 d (p<0.01 compared to TLR4+/+ mice), corresponding to an acceleration by 48 d." (PMID 24086519, 2013). "Recently, the impact of carrageenan on glucose tolerance, insulin resistance, and impaired insulin signaling in a mouse model was reported, consistent with the evidence that TLR4-mediated inflammation is involved in diabetes." (PMID 23766559, 2013). "Since the TLR4 signaling pathway is activated in diabetes and by carrageenan, we addressed systemic and intestinal inflammatory responses following carrageenan exposure in Bcl10 wild type, heterozygous, and null mice." (PMID 23766559, 2013). "The effect of TLR4 deficiency on the development of spontaneous diabetes in NOD mice was assessed by monitoring disease manifestation (BG>14 mmol/l on two consecutive days) in female TLR4+/+, TLR4+/− and TLR4−/− mice until an age of 220 d." (PMID 24086519, 2013). "Although secondary effects of these treatment regimens, such as LPS-mediated (cyto-)toxicity and/or tolerisation, cannot be excluded, the outcome of these experiments also point to a role of TLR4 in the development of diabetes in the NOD mouse." (PMID 24086519, 2013). "Recent studies show that FOXO1 promotes inflammation during diabetes by enhancing TLR4-mediated signaling, suggesting FOXO1 as a key mediator of inflammatory responses during obesity and diabetes." (PMID 22454632, 2012). "Taken together, these observations suggest a potential role for TLR2 and TLR4 in the pathology of diabetes." (PMID 22219634, 2011). "Furthermore, TLR4 mutant mice displayed hyperglycemia and hypoinsulinemia after diabetes induction to the same extent as control mice (respectively)." (PMID 40496562, 2025). "Chrysin also modulates the TLR4/NF-κβ pathway, ameliorating diabetes in rats." (PMID 40809172, 2025).